PSMD14 (proteasome 26S subunit, non-ATPase 14)
Diseases named in the same sentence as PSMD14 in open-access papers (continued):
Sharing a sentence is not in itself a finding about the gene and the disease.
tumor (continued). "Finally, ATP6AP1, PSMD14 and HSP90AB1 were chosen to validate the expressions in 63 cases of HCC tissues and the corresponding adjacent non-tumor tissues." (PMID 38327651, 2023). "The results showed that ATP6AP1, PSMD14, HSP90AB1 were generally highly expressed in tumor tissues." (PMID 38327651, 2023). "The deletion of PSMD14 and USP39 significantly inhibited tumor growth." (PMID 35627203, 2022). "Furthermore, DUB PSMD14 enhances cell migration and invasion in vitro via deubiquitinating GRB2, which is related to tumor metastasis." (PMID 35884607, 2022). "In ESCC, PSMD14 deubiquitinates and stabilizes SNAIL to promote tumor metastasis." (PMID 33897885, 2021). "Additionally, a notable decrease in PSMD14 expression was observed in adjacent non-cancerous tissues, highlighting its potential utility as a tumor biomarker with clinical relevance." (PMID 40475775, 2025). "Furthermore, our novel exploration links the PSMD14-HMMR axis to the establishment of an immunosuppressive tumor microenvironment, an aspect of PSMD14 biology not previously associated with its canonical deubiquitination function." (PMID 41488674, 2025). "While these studies establish a paradigm of PSMD14 activating individual oncogenic pathways in a context-dependent manner, its functional repertoire in LUAD, particularly the ability to co-regulate multiple core pathways and influence the tumor immune landscape, remained largely unexplored." (PMID 41488674, 2025). "In addition, by analyzing the expression of PSMD11 and PSMD14 in the tumor and normal groups in the three GEO cohorts, we found that all of them were significantly different and that the expression of PSMD11 and PSMD14 was higher in the tumor group than in the normal group." (PMID 40182048, 2025). "Then, we selected ATP6AP1, PSMD14 and HSP90AB1 as the candidate genes and verified the expressions in 63 cases of tumor tissues and the adjacent non-tumor tissues." (PMID 38327651, 2023). "We found that only ATP6AP1, PSMD14 and HSP90AB1, were generally existent and highly expressed in tumor tissue (data not shown)." (PMID 38327651, 2023).
infection (2 papers, 2019 to 2023). The state of being infected such as from the introduction of a foreign agent such as serum, vaccine, antigenic substance or organism. "After infection with sh2-PSMD14 and sh3-PSMD14 lentiviruses, mRNA and protein expression of PSMD14 were found to be considerably suppressed." (PMID 38053170, 2023). "Our study found a set of proteasome-encoding genes that included PSMA1, PSMD10, PSMD14 and PSMA4, that were all down-regulated during the early phase of infection." (PMID 30789917, 2019).
brain disorder (1 paper, 2016). A disease affecting the brain or part of the brain. "Recently, the down regulation of PSMD14 has been reported in relation with AD and other brain disorders." (PMID 27050411, 2016).
PSMD14 also shares sentences with these, for which no sentence is quoted: Intellectual disability (2 papers); prostate carcinoma (2); serous ovarian cancer (2); acute promyelocytic leukemia (1); autism (1); Cachexia (1); colon cancer (1); COVID-19 (1); dyslipidemia (1); epithelial ovarian borderline tumor (1); glioblastoma (1); gynecological cancer (1); Hepatic steatosis (1); Hepatitis (1); hypothyroidism (1); lipid metabolism disorders (1); mastitis (1); metastasis (1); metastatic tumor (1); monoclonal gammopathy (1); neck cancers (1); Obesity (1); peritonitis (1); preeclampsia (1); rectal cancer (1); Splenomegaly (1); steatosis (1); tongue cancer (1).